CATSPERQ (catsper channel auxiliary subunit theta)
Description:
Auxiliary component of the CatSper complex, a complex involved in sperm cell hyperactivation.
Synonyms: C8orfK29; TMEM249
Tractability: Antibody: UniProt predicts a signal peptide or a membrane-spanning region; its Gene Ontology location is reachable by antibodies, with medium confidence.
Gene: Protein-coding gene on chromosome 8 (144,352,219 to 144,354,954, reverse strand). Ensembl gene ENSG00000261587.
Subcellular location: Cell projection, cilium, flagellum membrane
Gene Ontology:
Biological process: flagellated sperm motility; sperm capacitation; spermatogenesis
Cellular component: CatSper complex; sperm principal piece
Genetic constraint (gnomAD): Loss-of-function variants: 15 observed, 20.09 expected, observed/expected ratio (o/e) 0.75, 90% interval 0.5 to 1.15. The upper end of that interval is the gene's LOEUF score, 1.15, which puts it in group 5 of 6, group 1 being the genes least tolerant of losing a copy. Missense variants: 348 observed, 324.83 expected, observed/expected ratio (o/e) 1.07, 90% interval 0.98 to 1.17. Synonymous variants: 165 observed, 141.92 expected, observed/expected ratio (o/e) 1.16, 90% interval 1.02 to 1.32.
Homologues: Orthologues: chimpanzee TMEM249 (98% identical), macaque TMEM249 (90% identical), dog TMEM249 (74% identical), pig TMEM249 (72% identical), mouse Tmem249 (66% identical), rabbit TMEM249 (66% identical).
Diseases named in the same sentence as CATSPERQ in open-access papers:
CATSPERQ is named in the same sentence as 2 diseases in open-access papers, as found by Europe PMC text mining. Sharing a sentence is not in itself a finding about the gene and the disease.
CATSPERQ shares sentences with these, for which no sentence is quoted: Infertility (1 paper); ovarian serous carcinoma (1).